LINC02802 (long independently transcribed non-coding RNA 2802)
Gene: Long non-coding RNA gene on chromosome 1 (144,135,212 to 144,250,375, reverse strand). Ensembl gene ENSG00000232527.
Diseases named in the same sentence as LINC02802 in open-access papers:
LINC02802 is named in the same sentence as 4 diseases in open-access papers, as found by Europe PMC text mining. Sharing a sentence is not in itself a finding about the gene and the disease. The quoted sentences say what the papers report.
lung adenocarcinoma (1 paper, 2025). A carcinoma that arises from the lung and is characterized by the presence of malignant glandular epithelial cells. "We further explored the mechanism underlying the aberrant upregulation of LINC02802 in lung adenocarcinoma." (PMID 40860186, 2025). "To further study the biological function of LINC02802 in the progression of lung adenocarcinoma, we selected H1975 and H1299 cell lines with the highest LINC02802 expression for further functional experiments." (PMID 40860186, 2025). "Specifically, in lung adenocarcinoma, we found that LINC02802 was significantly upregulated." (PMID 40860186, 2025). "Among them, LINC02802 was the most significantly upregulated and had not been reported in the progression of NSCLC, so we identified it as a potential target gene for further study of its function in lung adenocarcinoma." (PMID 40860186, 2025).
lung carcinoma (1 paper, 2025). "Given that LINC02802 was found to be highly expressed in cisplatin-resistant cell lines, it is hypothesized that the elevated expression of LINC02802 may be associated with cisplatin resistance in lung cancer." (PMID 40860186, 2025). "Importantly, LINC02802 overexpression partially rescued the inhibitory effects caused by LINC02802 knockdown on cell proliferation and migration, indicating that LINC02802 plays a crucial role in lung cancer cell proliferation and metastasis." (PMID 40860186, 2025). "Transwell assays also showed that overexpression of miRNA-1976 inhibited lung cancer cell migration, and overexpression of LINC02802 rescued this effect." (PMID 40860186, 2025). "CCK8 experiments confirmed that LINC02802 knockdown inhibited lung cancer cell proliferation, and colony formation experiments showed that LINC02802 knockdown significantly inhibited cell colony formation abilities." (PMID 40860186, 2025). "We constructed stable LINC02802 knockdown cell lines using shRNA, and qRT-PCR experiments verified the knockdown efficiency, showing that both shRNAs significantly inhibited LINC02802 expression in lung cancer cell lines." (PMID 40860186, 2025). "Further analysis of LINC02802 expression in lung cancer cell lines showed that, compared with normal lung epithelial cells, LINC02802 was significantly upregulated in most lung cancer cell lines, especially H1975 and H1299." (PMID 40860186, 2025). "To further confirm that SLC25A51 is a downstream target gene of LINC02802 in promoting lung cancer progression, we performed cell biology rescue experiments." (PMID 40860186, 2025). "We found that knockdown of NAT10 significantly reduced the expression of LINC02802, and treatment of lung cancer cells with the NAT10 inhibitor remodelin also downregulated LINC02802 expression." (PMID 40860186, 2025). "To further investigate whether LINC02802 affects cisplatin resistance, we conducted flow cytometry assays, which revealed that knockdown of LINC02802 significantly induced apoptosis in lung cancer cells." (PMID 40860186, 2025). "Given that LINC02802 regulates the mitochondrial NAD+/NADH ratio, and mitochondrial metabolism is closely intertwined with immune cell activation and function, it is plausible that the tumor immune microenvironment (TIME) may contribute to the upregulation of LINC02802 in lung cancer." (PMID 40860186, 2025). "Moreover, analysis of our previously published m6A-RIP-seq data from lung cancer cell lines revealed no enrichment of LINC02802 by the m6A antibody, suggesting that the expression of LINC02802 may not be associated with m6A modification (data not shown)." (PMID 40860186, 2025).
cancer (1 paper, 2025). A tumor composed of atypical neoplastic, often pleomorphic cells that invade other tissues. "LINC02802 is a long non-coding RNA (lncRNA) that has recently emerged as a potential regulator in cancer biology." (PMID 40860186, 2025). "Furthermore, hypoxia and nutrient competition within the TIME may further enhance LINC02802-mediated adaptation of cancer cell metabolism." (PMID 40860186, 2025).
tumor (1 paper, 2025). "Although its functions remain incompletely characterized, accumulating evidence suggests that LINC02802 is involved in modulating cellular metabolism and tumor progression." (PMID 40860186, 2025).